MIR378G (microRNA 378g)
Synonyms: hsa-mir-378g
Gene: MicroRNA gene on chromosome 1 (94,745,860 to 94,745,900, reverse strand). Ensembl gene ENSG00000263526.
Homologues: Orthologues: chimpanzee MIR378G (100% identical).